TREM1 (triggering receptor expressed on myeloid cells 1)
Diseases named in the same sentence as TREM1 in open-access papers (continued):
Sharing a sentence is not in itself a finding about the gene and the disease.
Sepsis (continued). "At present, various biomarkers (alone or in combination) are used in the diagnosis of sepsis, including procalcitonin (PCT), C-reactive protein (CRP), interleukin (IL), and soluble form of triggering receptor expressed on myeloid cells-1 (Strem-1)." (PMID 26192602, 2015). "Further, using siRNA silencing of TREM-1 in the mouse, Gibot and colleagues demonstrated the importance of the balanced activation of TREM-1 signaling during sepsis." (PMID 25505454, 2014). "Studies have shown that the expression of TREM-1 is elevated in vitro in the presence of bacteria or fungi as well as peritoneal fluid and tissue from infected patients but remains at normal levels in noninfectious inflammatory conditions and may be a therapeutic target for sepsis." (PMID 24772418, 2014). "In this study we evaluated in a human E. coli sepsis cohort, the role of PRR including TLR’s and Trem-1." (PMID 23414215, 2013). "TREM1-mediated amplification of proinflammatory immune responses worsens outcomes in models of infection such as sepsis and non-infectious models, including rheumatoid arthritis, pancreatitis, atherosclerosis, and chronic obstructive pulmonary disease." (PMID 41451290, 2025). "TREM-1 has been identified as a key regulator of pro-inflammatory innate immune responses in both infectious and non-infectious diseases, including CVD, atherosclerosis, multiple cancers, and sepsis." (PMID 41226426, 2025). "Overall, these data suggest that BTK inhibition via ibrutinib diminishes TREM-1-mediated PMN function, providing a potential clinical strategy for modulating immune responses driven by TREM-1, such as those involved in sepsis, inflammatory bowel disease, peripheral artery disease, and psoriasis." (PMID 41226426, 2025). "Safety Profile of GF9: Preclinical investigations in murine models of sepsis, colitis, and liver injury demonstrated that GF9 effectively inhibits TREM-1/DAP12 interactions, thereby attenuating excessive cytokine release while maintaining phagocytic capacity and bacterial clearance." (PMID 41226426, 2025). "Ligand-independent TREM-1 inhibitory peptides GF9 and GA31 (the latter in a form of macrophage-targeted lipopeptide complexes, GA31-LPC) were evaluated in animal models of pancreatic cancer, sepsis, pulmonary inflammation, and fibrosis." (PMID 41404075, 2025). "Inhibitor specificity and treatment timing effects of therapeutic TREM-1 blockade were also observed in sepsis and acute lung injury models, but not in fibrosis." (PMID 41404075, 2025). "Despite promising preclinical data and safety in humans, the first clinical inhibitor of TREM-1 (peptide LR12 or nangibotide) failed to reach significance for the primary endpoint in ASTONISH phase IIb sepsis trial." (PMID 39737196, 2024). "Importantly, despite promising results in disease models in small and large animals and safety in humans, the first clinical TREM-1 blocker, LR12 peptide (Nangibotide), failed in a recent phase IIb sepsis trial." (PMID 39418109, 2024). "Although clinical trials have not yet been conducted, efforts to develop drugs targeting TREM-1 for the treatment of sepsis are underway." (PMID 39081318, 2024). "To validate our findings, we extended the number of plasma samples for trauma (n = 23) and sepsis patients (n = 23) and performed quantitative ELISA to measure the contents of A2M, IL1F10, SYT13, and TREM1 in these samples at three time points (day 0, 3 and 5)." (PMID 38283341, 2023). "To conclude, our research emphasizes the potential of A2M, IL1F10, SYT13, and TREM1 as a composite set of biomarkers for distinguishing between non-infected trauma and sepsis patients." (PMID 38283341, 2023). "In this study, the septic patients without ALI had higher expression of TREM1, indicating that inflammatory response had an important role in the development of sepsis." (PMID 37700323, 2023).
Sepsis (continued). "TREM1 levels, however, increased only in plasma samples from trauma patients but not in those from sepsis patients over the course of time." (PMID 38283341, 2023). "Of particular interest is TREM-1, which has been previously reported to accentuate lung injury during ARDS and has shown promise as an inflammatory biomarker and as therapeutic target for sepsis and septic shock." (PMID 36552336, 2022). "Further research using both human and mouse in vivo models on the actions and relations of IRAK3 to other molecules (glucocorticoids, TREM-1, HMBG1, and HIF-1α) and inflammatory regulators will clarify insights and may improve treatment of sepsis." (PMID 35167625, 2022). "Additionally, mice treated with TREM-1/Fc had improved 7-day survival in LPS, CLP, and Escherichia coli-induced sepsis." (PMID 35784361, 2022). "Recently, we found that eCIRP can independently induce a systemic inflammatory response akin to sepsis through activation of TREM-1, however, the resultant effects on kidney function have not been thoroughly explored." (PMID 36246143, 2022). "TREM1 was closely related to Crohn disease and inflammatory bowel disease (IBD) and sepsis." (PMID 34221733, 2021). "Our findings are consistent with previous studies in Chinese Han populations, which also did not reveal a significant impact of the TREM-1 rs2234237 genotype on the 28-day outcome of patients in septic shock or the development of severe sepsis." (PMID 30832396, 2019). "Importantly, extracellular actin showed co-localization with TREM-1 in lung tissue sections from septic mice, which suggested that TREM-1 recognized actin during activation in sepsis." (PMID 28824642, 2017). "Due to the key role of TREM-1 in amplifying the inflammatory response, TREM-1 was identified as an essential regulator of innate immunity in sepsis syndrome, and it was confirmed to be an attractive target for the treatment of sepsis." (PMID 28824642, 2017). "Previous studies have reported that patients with sepsis had increased sTREM-1 and decreased membrane-bound TREM-1 expression on neutrophils compared to non-infectious systemic inflammatory response syndrome." (PMID 29201022, 2017). "TREM-1 deficiency has shown to be detrimental during endotoxaemia and polymicrobial sepsis, while in contrast, moderate levels of TREM-1 can improve survival during polymicrobial sepsis, but not endotoxaemia." (PMID 27253382, 2016). "TREM1 expression has been found to be decreased in sepsis but not in SIRS patients, indicating its potential as diagnostic marker." (PMID 25706641, 2015). "The results of these studies are in agreement with a previous study in Greek patients and re-confirm that the gene expression of TREM-1 at baseline is not different between sepsis, severe sepsis and septic shock." (PMID 25532536, 2014). "Furthermore, in a recent study by our group, gene transcripts of TREM-1 and of TNF were measured in circulating monocytes from 13 patients with severe sepsis and from seven patients with uncomplicated sepsis within the first 24 h diagnosis." (PMID 24350219, 2013). "In sepsis patients Trem-1 expression on neutrophils shows a negative correlation to the serum levels of TNF-α (r = −0,63; p < 0,005), IP-10 (r = −0,5; p < 0,035) and procalcitonin (r = −0,59; p < 0,007)." (PMID 23414215, 2013). "Serum sTREM-1 increases early in sepsis at levels related to disease severity, which is not the case for TREM-1 gene transcripts." (PMID 23861562, 2013). "While preliminary doses have not shown significant improvement, higher doses of this TREM-1 inhibitor may improve immune regulation during sepsis." (PMID 40406124, 2025). "As studies in sepsis have indicated the TREM-1 pathway as a potential therapeutic target, it is tempting to speculate that, like anti-IL-6R therapy, a beneficial effect of TREM-1 modulation in patients with COVID-19 could be also present." (PMID 34195785, 2021).
Sepsis (continued). "Transient sepsis might increase gene expression of TREM-1 as well, but circulating sTREM-1 levels are not influenced." (PMID 32508526, 2020). "Moreover, the additive effects of other SNPs in the TREM-1 gene—such as rs2234246, rs7768162 or rs9471535—on sepsis outcome have not been investigated in this study, but need to be considered." (PMID 30832396, 2019). "We supposed that the functional TREM-1 rs2234237 SNP that induces a change in the amino acid sequence and influences the biological function of TREM-1 might affect sepsis mortality and disease severity in a relatively large cohort of prospectively enrolled septic Caucasian patients." (PMID 30832396, 2019). "Next, expression of TREM-1 may be under the control of nuclear factor-κB, with engagement of TREM-1 during sepsis possibly leading to activation of several transcription complexes that synergize with NF-κB in order to elicit transcription of proinflammatory genes." (PMID 24959004, 2014). "Since TREM-1 is a pro-inflammatory receptor, it may be hypothesized that the observed decrease of TREM-1 expression upon aggravation to severe sepsis/shock may be a component of the immunoparalysis taking place in sepsis." (PMID 22050935, 2011). "Moreover, meta-analyses showed that sTREM-1 also had a moderate predictive capability (AUC: 0.82 and 0.78, respectively) in assessing adult sepsis mortality; however, there was no involved data to evaluate the prognostic value of TREM-1 expression in neonatal sepsis in those studies." (PMID 35935355, 2022). "This lack of differences between the stages of sepsis prompted us to investigate the early kinetics of TREM-1 and TREM-1." (PMID 25532536, 2014). "The increase in surface TREM-1 expression on monocytes and serum sTREM-1 concentrations was registered in patients with postoperative preclinical SIRS and no sepsis, in those with acute pancreatitis and pulmonary contusion." (PMID 24049646, 2012).
atherosclerosis (38 papers, 2013 to 2026). A disease characterized by the build-up of fatty material and calcium deposition in the arterial wall resulting in partial or complete occlusion of the arterial lumen. "In the Trem-1−/−-Apoe−/− model, TREM-1 deficiency significantly mitigates atherosclerosis by reducing monocytosis, inflammatory plaque formation, and expression of chemokine receptors like CX3CR1 on nonclassical monocytes." (PMID 41226426, 2025). "TREM-1 deletion or blockade was associated with a significant and profound (up to 60%) reduction in the development of both early and advanced atherosclerosis." (PMID 33814983, 2021). "Our study of elevated plasma sTREM1-1 levels in patients with ACS suggests that TREM-1 is involved in the inflammatory process underlying atherosclerosis and coronary plaque rupture, which lead to ACS." (PMID 33814983, 2021). "As a potent amplifier of acute and chronic inflammation, TREM1 has been linked with obesity, atherosclerosis, and AD." (PMID 31426806, 2019). "We believed in CVD, PGLYRP-1 alone or linked to PG is the putative ligand of TREM-1 implicated in atherosclerosis." (PMID 30205488, 2018). "High levels of TREM-1 are associated with cardiovascular and inflammatory diseases risks and the most recent studies have showed that TREM-1 deletion or blockade is associated with up to 60% reduction of the development of atherosclerosis." (PMID 28771614, 2017). "Collectively, these results from human atherosclerosis patients and our findings from an experimental model of atherogenesis, where deficiency in TREM-1 conferred significant protection, establish a major pathogenic role for TREM-1 in atherosclerosis." (PMID 27762264, 2016). "Trem1−/− mice were backcrossed onto the atherosclerosis-susceptible Apoe−/− background and 6–8-week-old female Trem1−/−Apoe−/− and Trem1+/+Apoe−/− mice were concurrently placed on a high-fat, high-cholesterol-containing diet (HFCD)." (PMID 27762264, 2016). "Additionally, a genetic study showed a strong correlation between TREM-1 gene polymorphisms and the severity of atherosclerosis in a Russian population." (PMID 41451290, 2025). "Loss of TREM1 may constitute a new treatment for atherosclerosis by regulating foam cell formation and monocyte/macrophage proinflammatory responses." (PMID 35722091, 2022). "Studies of trem−/− mice as well as pharmacological inhibition of TREM-1 suggested that TREM-1 deficiency/inhibition significantly reduced atherosclerosis growth (in mice) and induced a plaque phenotype characterized by reduced macrophage infiltration and necrotic core size." (PMID 33814983, 2021). "Additionally, genetic analysis revealed that TREM-1 gene polymorphisms are closely associated with atherosclerosis severity in a Russian population." (PMID 30993014, 2019). "Studies which endeavored to find any polymorphisms in TREM-1 gene expression associated with atherosclerosis remain elusive in regard to their overall conclusion—however, it has been found that sTREM-1 increases when AMI is associated with single nucleotide polymorphisms (SNPs))." (PMID 30205488, 2018). "Chronic inflammation, and progressive NIH, and atherosclerosis are associated with vessel thrombosis and stenosis, and increased expression of inflammatory mediators TREM-1, regulated by TLR-4 activation, might play a role in sterile inflammation in AVF maturation failure and patency of AVF." (PMID 36147190, 2022). "A study of atherosclerosis in mice showed that pravastatin inhibited TREM-1/DAP12, hence improving atherosclerosis." (PMID 40319222, 2025). "Pharmacological suppression of TREM-1 or epigenetic TREM-1 modification reduces atherosclerosis and the incidence of AMI in a mouse model with a notably low death rate, and it can also help individuals who are at risk of endocarditis inflammation." (PMID 41226426, 2025). "Since the pathological processes underlying both atherosclerosis and CAVD are highly similar, TREM1 is a promising target to prevent and/or treat CAVD." (PMID 38333413, 2024).
atherosclerosis (continued). "TREM1 expression showed positive correlation with the plaque size and macrophage infiltration during the development of atherosclerosis." (PMID 38333413, 2024). "This establishes TREM-1 as not only a regulator of inflammation but also potentially as a modulator of atherosclerosis via macrophage and neutrophil activation." (PMID 36856919, 2023). "The immune-associated genes in both atherosclerosis and osteoporosis from WGCNA mainly included TREM1, CYBB, CCR1, CD83, CD52, IL7R, and THBS1." (PMID 35937806, 2022). "The deleterious role of TREM-1 over-activation is established in acute diseases such as septic shock or myocardial infarction, as well as during chronic disorders such as atherosclerosis." (PMID 36699032, 2022). "Inflammation mediated by myeloid cells trigger receptors 1 (TREM-1) is important for atherosclerosis development, while sirtuin 6 (Sirt6) levels decrease in atheroscleoritc plaque." (PMID 30993014, 2019). "A growing body of literature supports a role for TREM-1 in several inflammatory diseases, such as atherosclerosis, myocarditis, diabetes, and others." (PMID 31325960, 2019). "Reduction in ABCA1 and consequently of cholesterol efflux, as well as increased abundance of TREM-1 in rafts, are recognized factors promoting accumulation of cholesterol in macrophages and inflammation, two key elements in pathogenesis of atherosclerosis." (PMID 31344124, 2019). "We foresee that any intervention that will downplay the role of TREM-1 will be beneficial in the long run to prevent atherosclerosis and its detrimental consequences of AMI, stroke, or ischemia of the extremities." (PMID 30205488, 2018). "In atherosclerosis, the role of TREM-1 is found to be in chronic inflammation, leading to macrophages, leukocyte apoptosis, and necrosis, which contribute to fatty streak buildups." (PMID 30205488, 2018). "LR-12 has been shown to block TREM-1 and reduces its activation of monocytes/macrophages to form foam cells in atherosclerosis pathogenesis." (PMID 30205488, 2018). "TREM-1 protein levels have been related to numerous diseases where inflammation and inflammatory cell extravasation play central roles, such as atherosclerosis, acute myocardial infarction, and critical limb ischemia." (PMID 28771614, 2017). "It has been previously demonstrated that TREM-1 is crucially involved in leukocyte recruitment after myocardial infarction and atherosclerosis." (PMID 28771614, 2017). "At 16 weeks post HFCD feeding, Trem1−/−Apoe−/− mice exhibited a 40% reduction in the overall extent of atherosclerosis in the aorta." (PMID 27762264, 2016). "In particular, our results identify skewed monocyte differentiation and enhanced lipid accumulation as novel mechanisms through which TREM-1 can promote atherosclerosis." (PMID 27762264, 2016). "Our findings thus identify TREM-1 as a key innate immune receptor participating in the chronic inflammatory process in atherosclerosis." (PMID 27762264, 2016). "Since there is an important role of monocytes and macrophages in atherosclerosis and plaque instability, TREM-1 activation in atherosclerosis can be related to stages and extent of atherosclerotic disease." (PMID 27148736, 2016). "Our data so far demonstrated that TREM-1 promotes atherosclerotic lesion progression in an experimental atherosclerosis model in vivo by aggravating monocytosis and monocyte/macrophage infiltration of aortas." (PMID 27762264, 2016). "These included the LXR/RXR Activation, Atherosclerosis Signaling and TREM1 Signaling pathways among others." (PMID 23951329, 2013). "Notably, emerging evidence suggests that TREM-1 is also involved in the development and progression of cardiovascular diseases, such as atherosclerosis and atrial fibrillation." (PMID 41511954, 2026). "Overall, in early atherosclerosis, TREM-1 is increased in vascular macrophages." (PMID 41226426, 2025).